NR2F1 (nuclear receptor subfamily 2 group F member 1)
Diseases named in the same sentence as NR2F1 in open-access papers (continued):
Sharing a sentence is not in itself a finding about the gene and the disease.
cancer (53 papers, 2009 to 2025). A tumor composed of atypical neoplastic, often pleomorphic cells that invade other tissues. "In a similar approach, the role of NR2F1, a protein encoded by the NR2F1 gene which is also involved in many human cancers, was investigated." (PMID 37159817, 2023). "NR2F1 downregulation is related to high cancer mutation rates, immune responses, and cell infiltrations, and it is upregulated in inflammatory cancer-associated fibroblasts (CAFs)." (PMID 36661515, 2023). "Cancer mutation rates, immune responses, and immune cell infiltrations were lower in high NR2F1 tumors, whereas the infiltration of stromal cells including cancer-associated fibroblasts (CAFs) was higher." (PMID 35740627, 2022). "The association between NR2F1 and cancer-associated fibroblast (CAF) infiltration and immunotherapeutic responses were also researched." (PMID 36230565, 2022). "Previous studies have shown that NR2F1 is mainly implicated in brain cell cycle control, cancer cell dormancy, invasion and metastasis." (PMID 35936005, 2022). "We also found that NR2F1 was positively correlated with the infiltration of immunosuppressive cancer-associated fibroblasts (CAFs)." (PMID 36230565, 2022). "Further immune infiltration analysis evidenced that NR2F1 expression exhibited positive relation to cancer-associated fibroblast (CAF) infiltration." (PMID 36230565, 2022). "The induction of NR2F1 by AZA + atRA led to reprogramming of the epigenetic landscape of cancer cells, and the treatment caused a global increase in the level of the repressive chromatin state." (PMID 34208521, 2021). "NR2F1 is also implicated in hypoxia-driven glycolysis and migration of cancer cells." (PMID 37612452, 2023). "NR2F1’s involvement in EMT and chemoresistance, along with ATF3’s association with heightened treatment resistance, rendered these factors pivotal in cancer progression." (PMID 40612060, 2025). "NR2F1 is recognized as a key dormancy promoter, as it drives the expression of specific cancer dormancy markers, such as SOX9 and RARβ, within the TME." (PMID 40977686, 2025). "Subsequently, we analysed the relationship between NR2F1 and BC prognosis using pan-cancer dataset downloaded from the UCSC database and prognostic dataset from the TCGA dataset in a previous study." (PMID 39219375, 2024). "Dormant state induction in cancer cells via NR2F1 overexpression has been demonstrated in numerous experiments in vitro, in patient-derived organoids, and in vivo." (PMID 38418814, 2024). "Owing to the controversial role of NR2F1 in different cancers, we will further explore the related molecular mechanisms in future studies." (PMID 39219375, 2024). "Next, qRT-PCR and western blot revealed that NR2F1 was increased in BC tissues versus normal para-cancer tissues (*p < 0.05)." (PMID 39219375, 2024). "Experimental strategies aimed at increasing the expression of dormancy-related factors such as p38 and NR2F1 have also been shown to induce cancer dormancy and prevent metastatic outgrowth." (PMID 36757577, 2023). "We revealed, for the first time in C4-2B cells, that PF-271 blocked FAK phosphorylation and increased FAK nuclear translocation, through which increased NR2F1 expression and inhibited cyclin D1 expression, in turn, induced cancer cell dormancy." (PMID 37821954, 2023). "Nuclear receptor subfamily 2 group F member 1 (NR2F1) has been shown to modulate gene expression during cancer development and growth." (PMID 37612452, 2023). "In the context of BLCA, dysregulated expression of NR2F1 has been verified in cancer cell proliferation, invasion, and metastasis." (PMID 38103068, 2023). "NR2F1 regulates the progression of cell differentiation, cancer progression, and central and peripheral neurogenesis." (PMID 35090432, 2022).
cancer (continued). "In particular, evidence from accumulative studies has suggested a direct influence of NR2F1 on cancer progression via modulating cancer cells’ ability to migrate, proliferate or respond to external signals, including hormones." (PMID 36230565, 2022). "Single-cell sequencing showed that NR2F1 was almost exclusively expressed in CAFs, and rarely in cancer cells." (PMID 35740627, 2022). "NR2F1 expression was higher in treatment naïve than in treated CAFs, which was opposite the results that were observed in cancer cells." (PMID 35740627, 2022). "The association of NR2F1 levels with the Nottingham histological grades and the cell proliferation marker MKI67 was studied for the pathological assessment of cancer cell proliferation." (PMID 35740627, 2022). "NR2F1 was rarely expressed in cancer cells and was most prominently expressed in CAFs, as assessed by cell types in a single-cell sequence cohort and validated in another cohort." (PMID 35740627, 2022). "Our previous findings have demonstrated that atRA treatment can be used to induce dormancy in SACC cells, and its effects on cancer dormancy resulted directly from modulation of NR2F1." (PMID 33990215, 2021). "A positive correlation of NAS1 with NR2F1 expression and ∆Np63 with miR-205 was also observed in the TCGA pan-cancer cohort, while the expression of NR2F1 was negatively correlated with the expression of both ∆Np63 and miR-205." (PMID 34475402, 2021). "In this study, we show that lncRNA NAS1 is highly expressed in mesenchymal-like BCSCs and reveal its functions to promote cancer cell dissemination and metastatic dormancy in the lungs by regulating the NR2F1-ΔNp63 axis." (PMID 34475402, 2021). "Tumorsphere formation and ALDH+ fraction of the cancer cells that were impaired by NAS1 were also rescued by NR2F1 knockdown." (PMID 34475402, 2021). "We continued to analyze the downstream molecular events of NAS1–NR2F1 to promote tumor cell dormancy, by RNA-sequencing analysis of cancer cells after NAS1 knockdown or NR2F1 overexpression." (PMID 34475402, 2021). "The MNCs contain 0–3 small/weak NR2F1 signals per nucleus and the cancer cell two similarly small signals." (PMID 30322396, 2018). "Our experimental model studies of DTC dormancy revealed that NR2F1, an orphan nuclear receptor of the retinoic acid receptor family, is commonly downregulated in human cancer and metastatic tissues." (PMID 30322396, 2018). "This included the pro-apoptotic Ddit3 and transcription factor Nr2f1, which exerts anti-AP-1 activity and are a mediator of the anti-cancer effect of retinoic acid." (PMID 26427040, 2015). "We next examined the effects of RA on the epigenetic signatures at the Nr2F1 gene in F9 embryonal carcinoma stem cells." (PMID 23666625, 2013). "Both DMBA- and MNU-induced carcinomas from Mcs1a resistant congenic animals had strongly increased Nr2f1 transcript levels, as compared with DMBA- and MNU-induced carcinomas from susceptible control congenic rats (P<0.001)." (PMID 23785296, 2013). "However, critical questions remain about NR2F1’s regulatory mechanisms, its role in therapy resistance across cancer types, and how best to target it therapeutically." (PMID 40955667, 2025). "In addition, altered NR2F1 expression is frequently observed in various cancers and is considered a prognostic marker or potential therapeutic target." (PMID 40204944, 2025). "Interestingly, NR2F1 expression is re-upregulated in metastatic or resuscitated breast cancer cells, suggesting its dynamic role in cancer progression." (PMID 40977686, 2025). "As the fold change threshold increased (>3.0), the number of differentially expressed genes decreased, but core regulatory genes such as ADGRL2, NR2F1, S100A16, and KRT19 remained consistently altered, highlighting isoform-specific regulation of key cancer-associated genes." (PMID 41300774, 2025). "The compound C26 was reported to induce cancer cell dormancy by increasing NR2F1 activity." (PMID 39163135, 2024).
cancer (continued). "Consistently, NR2F1 was shown as a marker for dormant cancer cells." (PMID 37821954, 2023). "Conceivably, maintaining the NR2F1 signal could reduce early dissemination of cancer cells and may represent a potential therapeutic option in EC." (PMID 37612452, 2023). "Using single-cell sequence cohorts, we found that NR2F1 was predominantly expressed in cancer-associated fibroblasts, particularly in inflammatory type, rather than in cancer cells." (PMID 35740627, 2022). "Simultaneously, NR2F1 was capable of modulating the drug resistance of cancer cells." (PMID 36230565, 2022). "Therefore, it was of interest to investigate the pathway that is involved with NR2F1 expression solely within cancer cells." (PMID 35740627, 2022). "Although further studies are warranted for validation, the expression of cancer dormancy markers, i.e., NR2F1, might be predictive in achieving better postoperative survival outcome in patients undergoing conversion surgery." (PMID 31905818, 2019). "The discrepancy suggests that NR2F1 may have different functions depending on cancer types." (PMID 39219375, 2024). "Therefore, we performed gene set enrichment analysis exclusively on cancer cells from single-cell sequence cohorts and found that there was no consistent enrichment of metastasis-related, stem cell-related gene sets or suppression of cell proliferation-related gene sets in NR2F1 high cancer cells." (PMID 35740627, 2022). "Notably, our data indicate that both NAS1 and NR2F1 play dual roles in cancer to promote tumor invasion but inhibit proliferation, which is seemingly conflicting for cancer progression but actually both contribute to the accumulation of dormant DTCs in metastatic organs." (PMID 34475402, 2021). "A plausible explanation for this observation could be that Nr2f1 transcript levels in an unidentified progenitor (or perhaps cancer-initiating) RMEC population may show similar substantial differences, which could be masked by other cell types present in the whole mammary gland or RMEC samples." (PMID 23785296, 2013). "NR2F1 itself plays a critical role in inhibiting the transcription of ρNp63, thereby promoting EMT and cancer dormancy." (PMID 40977686, 2025). "Considering the significant role of the STAT3 pathway in both fibrotic diseases and cancer metastasis during EMT,37, 38, 39, 40, 41, 42 we proceeded to explore the complex connection between NR2F1 and STAT3." (PMID 40641526, 2025). "Dormant cancer cells are non-proliferating quiescent cells (albeit transcriptionally active) that have undergone G0-G1 cell cycle arrest with downregulated proliferation-related markers such as Ki67 and pRb and high expression levels of dormancy-associated markers, including NR2F1." (PMID 40866498, 2025). "The study concluded that NR2F1 might be underlying a potential mechanism of the recurrence and metastasis of SACC because its lower expression in SACC samples compared to the normal salivary gland tissues was associated with cancer cell dormancy as well as cell migration and metastasis." (PMID 37159817, 2023). "Mechanistically, NAS1 binds to NR2F1 mRNA and promotes its translation by recruiting the RNA-binding protein PTBP1, thereby leading to NR2F1-mediated transcriptional suppression of ΔNp63, which induces EMT and promotes dormancy of cancer cells in the lungs." (PMID 39937018, 2025). "Examination of seven commonly used anti-NR2F1 antibodies in different human cancer and stem cells as well as in wild type and null mice revealed that NR2F1 nucleolar localization is artificial and has no functional role." (PMID 40204944, 2025). "NR2F1 was mainly expressed in CAF and cancer epithelial cell clusters." (PMID 37306188, 2023).
cancer (continued). "NR2F1 was predominantly expressed in CAFs, particularly inflammatory CAFs, rather than in cancer cells, consistently in the two single-cell sequence cohorts." (PMID 35740627, 2022). "In the same study, cancer cells, including PC3 PCa treated with 5-azacitidine (AZA, an FDA-approved drug), and all-trans retinoic acid (atRA) upregulated dormancy genes, including NR2F1, SOX9, RARβ, and p21, and downregulated Ki67 and P-ERK1/2." (PMID 34208521, 2021). "Given the importance of Notch signaling in many cancers, the ability of Nr2f1 to promote a Notch-like phenotype in absence of canonical Notch signaling in adult NSCs suggests that it could be an efficient factor for cancer SC maintenance." (PMID 40864701, 2025). "Finally, NR2F1 expression was higher in CAFs without treatment compared to those treated with chemotherapy, whereas NR2F1 expression was higher in cancer cells that underwent treatment compared to those that are not treated." (PMID 35740627, 2022). "On the contrary, the expression NAS1 was not affected by NR2F1 in cancer cells." (PMID 34475402, 2021). "Moreover, a detailed survey of immunohistochemical staining of human cancers indicated that SRPK1, KIF3B, C14orf142, NR2F1, and TMEM229B have significantly increased expression in the invasive zone of the primary tumors of these cancers as delineated by a pathologist." (PMID 29904055, 2018). "Dormant cancer cells are under cell cycle arrest, are neither actively proliferative nor apoptotic, and express reduced levels of Ki67 and cell cycle-related genes but higher levels of dormancy makers, such as the nuclear receptor subfamily 2 group F member 1 (NR2F1)." (PMID 37821954, 2023).
neurodevelopmental disorder (17 papers, 2019 to 2026). A behavioral and cognitive disorder with onset during the developmental period that involves impaired or aberrant development of intellectual, motor, or social functions. "Bosch‐Boonstra‐Schaaf optic atrophy syndrome (BBSOAS, OMIM #615722) is a neurodevelopmental disorder caused by pathogenic variants in NR2F1." (PMID 39972940, 2025). "Previous studies showed that NR2F1 point mutation caused neurodevelopmental disorders diseases such as Bosch‐Boonstra‐Schaaf optic atrophy syndrome (BBSOAS) in vivo, which suggests that the NR2F1 was vital in the development of the nervous system." (PMID 38041497, 2024). "Mutations of Nr2f1 are highly related to neurodevelopmental disorders (NDDs), such as intellectual disability (ID) and autism spectrum disorders (ASD), and mutations of the Nr2f2 gene are associated with congenital heart defects (CHDs)." (PMID 37751231, 2023). "Bosch–Boonstra–Schaaf optic atrophy syndrome (BBSOAS) is a rare neurodevelopmental disorder caused by loss-of-function variants in the Nuclear Receptor Subfamily 2 Group F Member 1 (NR2F1)." (PMID 36221391, 2022). "Finally, using the NR2F1 gene and BBSOAS as a paradigm of monogenic rare neurodevelopmental disorder, we aim to set the path for future explorations of causative links between impaired brain development and the appearance of symptoms in human neurological syndromes." (PMID 35455940, 2022). "(Likely) pathogenic variants in NR2F1 are associated with Bosch‐Boonstra‐Schaaf optic atrophy syndrome (BBSOAS, OMIM #615722), a rare neurodevelopmental disorder." (PMID 39972940, 2025). "This is consistent with previous findings on involvement of NR2F1 and NR2F2 in development of different brain structures in various animal models, regulation of neurodevelopmental timing, and their association with neurodevelopmental disorders in humans." (PMID 38177910, 2024). "Recently, lnc-Nr2f1 was reported to play a critical role in regulating neurodevelopmental disorders." (PMID 31862000, 2019).
neurological disorders (4 papers, 2019 to 2025). "Impaired NR2F1 function can cause neurological disorders, possibly because it regulates neocortical morphology through region-specific modulation during neurodevelopment." (PMID 40025604, 2025). "Therefore, our findings open new perspectives for future investigation on the role of NR2F1 in mitochondrial dysfunction associated with the pathogenesis and progression of neurological disorders." (PMID 37260288, 2023). "Specifically, 9330111N05Rik was reduced in TNI mice and restored by EA, while 9330111N05Rik was found to be upstream to the Nr2f1 gene that is known to be proneurogenic and contribute to neurological diseases." (PMID 37189648, 2023).
metabolic disorders (1 paper, 2023). "Accordingly, the upregulation of NR2F1 may have a significant impact on the hormonal induction of metabolic disorders in LN fetuses and postnatal life." (PMID 37445858, 2023).
NR2F1 also shares sentences with these, for which no sentence is quoted: ovarian carcinoma (5 papers); colon cancer (2); deafness (2); diabetes (2); Down syndrome (2); endometrial cancer (2); epilepsy syndrome (2); infantile spasms (2); schizophrenia (2); adenoma (1); adrenal hypoplasia congenita (1); antithrombin deficiency (1); atypical Rett syndrome (1); behavioral disorders (1); cervical cancer (1); colorectal adenocarcinoma (1); congenital stationary night blindness (1); developmental and epileptic encephalopathy (1); Epileptic spasm (1); ethylmalonic encephalopathy (1); fragile X syndrome (1); genetic disorders (1); head and neck cancer (1); hepatocellular carcinoma (1); Hirschsprung disease (1); Insulin resistance (1); Lissencephaly (1); macular degeneration (1); MELAS syndrome (1); Miller-Dieker syndrome (1).
A further 14 diseases each share a sentence with NR2F1 in 1 paper.